MMP2 (matrix metallopeptidase 2)
Diseases named in the same sentence as MMP2 in open-access papers (continued):
Sharing a sentence is not in itself a finding about the gene and the disease.
colon carcinoma (continued). "The EMT was significantly enhanced in FABP4-overexpressed colon cancer cells, as evidenced by the upregulation of Snail, MMP-2 and MMP-9, and the downregulation of E-cadherin." (PMID 33088219, 2020). "In this study, LINC00662 overexpression distinctly expedited the protein levels of VEGF and MMP2, and LINC00662 knockout significantly inhibited the protein levels of VEGF and MMP2 in colon cancer cells." (PMID 31900207, 2020). "By comparing the transcriptomic profile of colon cancer-cocultured MCs versus control MCs, we identified a number of deregulated genes, such as MMP-2, VEGF-A, PDGF-A, COX2, NOTCH1 and ISG15, which contribute to the enrichment of cancer-related pathways." (PMID 30987352, 2019). "In human colon cancer, it has been reported that the expression of MMP2, 7, and 9 correlates with an increased progression of cancer." (PMID 29966001, 2018). "It showed that andrographolide suppresses the invasion ability of colon cancer cells via inhibition of MMP-2 activity and attenuation of the ERK signaling pathway." (PMID 30359388, 2018). "Andrographolide has also been shown to have anti-invasive activity against colon cancer cells via inhibition of MMP-2." (PMID 30359388, 2018). "miR-340 treated colon cancer cells expressed significantly less MMP-2 and MMP-9 than pCMV treated cells." (PMID 29435169, 2018). "Targeting MMP-2 by miR-29b is a mechanism whereby American ginseng hexane extract suppresses the migration of colon cancer cells." (PMID 28630860, 2017). "Red wine polyphenolic extracts effectively reduced also the development of colon carcinoma by blunting tumour vascularization and inhibiting pro-angiogenetic key factors including MMP-2." (PMID 27589705, 2016). "MMP2 expression was hardly observed in normal colon mucosa, but markedly high in prime colon cancer and much higher in metastasis cancer tissue in colon cancer patients." (PMID 27791203, 2016). "MMT assays showed that HCT-15/RLuc/eIF4E, HCT-15/Rluc/VEGF-C, HCT-15/Rluc/MMP-2 grew faster than parental HCT-15/Rluc colon cancer cell line." (PMID 27907907, 2016). "We found that eIF4E, VEGF-C and MMP-2 were up-regulated in colon cancer, and their expression frequencies are higher in cancerous tissues than in normal control tissues." (PMID 27907907, 2016). "We next investigated the effect of eIF4E, VEGF-C, MMP-2 and E-cadherin on lung metastasis of colon cancer cells in mouse model, which mimics the clinical status of tumor metastases to distant sites." (PMID 27907907, 2016). "We furthermore investigated the expression of eIF4E, VEGF-C, MMP-2 and E-cadherin in primary site of patient-derived colon cancer xenografts." (PMID 27907907, 2016). "The result suggested that overexpression of eIF4E, VEGF-C, and MMP-2 promote the colon cancer cell growth." (PMID 27907907, 2016). "Matrix metalloproteinases (MMPs) produced by TAMs, such as MMP9 and MMP2 are required for the tumor cell invasion in colon cancer." (PMID 26799669, 2016). "Among these protein factors, eIF4E dominates the regulation of VEGF-C, MMP-2 and E-cadherin, and is a key factor for colon cancer metastasis." (PMID 27907907, 2016). "We therefore compared MMP2 expression in normal colon mucosa, prime colon cancer tissue and metastasis cancer tissue." (PMID 27791203, 2016). "In particular, MMP-2 and MMP-9 have been implicated to play a role in colon cancer progression and metastasis in animal models and patients." (PMID 27409174, 2016). "Utilizing the stable HCT-15/Rluc cell lines (HCT-15/RLuc/eIF4E, HCT-15/Rluc/VEGF-C, HCT-15/Rluc/MMP-2, HCT-15/Rluc/E-cadherin and parental HCT-15/Rluc), we investigated the effect of eIF4E, VEGF-C, MMP-2 and E-cadherin on the colon cancer cell growth." (PMID 27907907, 2016). "CCL9 (and CCL15) secreted by mouse and human colon cancer cells has been shown to recruit immature myeloid cells (iMCs), which produce matrix metalloproteinases MMP2 and MMP9 required for successful colonization of the liver." (PMID 25882816, 2015).
colon carcinoma (continued). "MMP-2 mRNA in colon cancer tumors is mainly localized in fibroblasts, and it seems that the main source of MMP-2 in colorectal tumors is fibroblasts." (PMID 24395652, 2014). "MMP2 expression was restrained after interfering HIF-1α expression in HCT116 colon cancer cells under hypoxia, by using siRNA." (PMID 25013467, 2014). "In particular, matrix metalloproteinase 2 (MMP-2) and MMP-9, known as gelatinases, have been implicated to play a significant role in colon cancer progression and metastasis." (PMID 24395652, 2014). "Among the MMP family members, MMP-2 and -9 are important molecules for cancer invasion, and are highly expressed in breast and colon cancer cells." (PMID 23426077, 2013). "p38-MAPK also modulated the inhibition of migration in 17β-estradiol-treated human colon cancer cells by inhibition of MMP-2/-9 expression." (PMID 23710144, 2013). "Strikingly, we found that TPX2 knockdown significantly attenuated the migration and invasion ability of colon cancer cells, which was further shown to be mechanistically associated with AKT-mediated MMP2 activity." (PMID 24341487, 2013). "Here, we have demonstrated that miR-29b and MMP-2 are key players in the ability of HAG to suppress colon cancer cell migration." (PMID 24130681, 2013). "Our study supports the understanding that targeting MMP-2 by miR-29b is a mechanism by which HAG suppresses the migration of colon cancer cells." (PMID 24130681, 2013). "Several drugs such as goniothalamin and 17β-estradiol were reported to inhibit the migration of lung and colon cancer cells by attenuating MMP-2 and MMP-9 activities, respectively." (PMID 23710144, 2013). "Two major matrix metalloproteinases (MMPs) in colon cancer, MMP-2 and MMP-9, were then studied using gelatin zymography." (PMID 19603013, 2009). "In colon carcinoma cells, TZDsinduce matrix metalloproteinase 2 (MMP2) and membrane type 1-MMP (MT1-MMP)activation and concomitantly increase tumor cell invasion through generation ofROS and activation of the ERK cascade." (PMID 18596912, 2008). "In vitro MMP-2 expression levels by colon cancer cell lines containing the CC genotype were indeed higher compared with cells with the CT genotype." (PMID 18506186, 2008). "Previous studies have shown that the induction of E-cadherin expression led to the suppression of MMP-2 activity in human colon carcinoma cells, reduced cellular invasion in prostatic adenocarcinoma, and down-regulated the expression of various types of MMPs in highly invasive bronchial tumor cells." (PMID 40806251, 2025). "To investigate whether MMP-2 inhibition could downregulate PD-L1 in colon cancer cells, we conducted in vitro experiments using the SW480 colon cancer cell line." (PMID 40611940, 2025). "Specifically, MMP-2 selective MMP-2 inhibitor SB-3CT or siRNA-mediated knockdown of MMP-2 in colon cancer cell lines resulted in a significant reduction in PD-L1 expression, a crucial immune checkpoint protein, suggesting a regulatory axis between MMP-2 and PD-L1 in COAD." (PMID 40611940, 2025). "SW480 colon cancer cell line was transfected with MMP-2 siRNA to knock down MMP-2." (PMID 40611940, 2025). "Notably, the injection of Cd-O2/N2 atomized gas statistically significantly amplified MMP-2 expression in the colon tumors of the CC mice relative to the blank and control groups (C-Control, C-S-Blank, and C-S-Control: p < 0.05)." (PMID 38535948, 2024). "Both gelatinases (MMP-2 and MMP-9) are closely associated with cancer invasion and progression, and their elevated expression has been connected to lower survival rates among colon cancer patients." (PMID 39683504, 2024). "Similarly, a decrease in the invasion of colon carcinoma cells HT-29 in a 2D model by inhibiting MMP-2 after 48 h of exposure of these to 200 μg/mL of fucoidan was reported." (PMID 37298837, 2023). "However, another study has reported that hsa_circ_0007843 promotes the progression of colon cancer by sponging miR-518c-5p to regulate MMP2 expression." (PMID 37981573, 2023).
colon carcinoma (continued). "Therefore, the potential treatment of Ca and Cal alone and combination with LPS stimulated HCT116 colon cancer cell lines were assessed for the expression of the MMP-2 and MMP-9 functions and Cal- and CA-treated cells." (PMID 36235161, 2022). "In this work, we have developed a strategy for the MMP2 MALDI spatial protein quantification determination by using a peptide probe, and this method has been successfully applied into the detection of the expression and location sites of MMP2 in colon cancer and normal tissue." (PMID 34976953, 2021). "Moreover, the activity levels of Pro-MMP2 were significantly higher in colon cancer sera compared to healthy sera." (PMID 34830271, 2021). "Our results show that LPE is able to inhibit the IL-6-dependent cell migration and invasiveness associated with the up-regulation of MMP-2 expression levels and that these effects are correlated to the STAT3 phosphorylation in human primary T88 and T93 colon cancer cells." (PMID 34885656, 2021). "Furthermore, we demonstrated that LPEs behave as anti-inflammatory agents able to prevent or counteract the invasiveness of colon cancer cells, mainly by the inhibition of IL-6-dependent effects induced on MMP-2 activity and expression." (PMID 34885656, 2021). "Other HIF-1 target genes with proven roles in colon carcinoma cell invasion include vimentin, keratins 14, -18, -19, fibronectin 1, matrix metalloproteinase 2 (MMP-2), urokinase-type plasminogen activator receptor (uPAR), cathepsin D, and autocrine motility factor (AMF)." (PMID 33276489, 2020). "Finally, FABP4 overexpression improved EMT progression of colon cancer, as evidenced by the upregulation of Snail, MMP-2 and MMP-9, the downregulation of E-cadherin." (PMID 33088219, 2020). "RUNX3 can inhibit the invasion and metastasis of human colon cancer HT-29 cells, and the mechanism may be related to decreased expression of MMP-2 and MMP-9." (PMID 32184893, 2020). "The aim of this study was to investigate association of polymorphisms rs1799750 in MMP-1, rs243865 in MMP-2, rs11568818 in MMP-7, rs2252070 in MMP-13 and rs28366003 in MT2A, together with serum Zn level, with occurrence of breast, lung and colon cancer in Poland." (PMID 32765800, 2020). "Poudyal study showed that PQR could induce the expression of miR-29b with matrix metalloproteinase-2 (MMP-2) as a target, thus inhibiting the migration of colon cancer cells." (PMID 33381041, 2020). "In the present study we analyzed whether polymorphisms rs28366003 in MT2A, rs1799750 in MMP-1, rs243865 in MMP-2, rs11568818 in MMP-7 and rs2252070 in MMP-13 genes are associated with the risk of breast, lung or colon cancer among polish subjects." (PMID 32765800, 2020). "Our experimental results are consistent with the results obtained in some previous studies, indicating that P2 × 7 receptor can regulate the expression of MMP-2, E-cadherin, N-cadherin, Vimentin, Zeb1, and Snail, and affect the invasion and migration of colon cancer cells." (PMID 33330466, 2020). "Furthermore, this down-regulation of REV3L also diminished colon cancer cell migration, and down-regulated MMP-2 and MMP-9." (PMID 29435169, 2018). "The expression of MMP-2 and -9 is higher in colon tumor tissues than in normal tissues." (PMID 28634392, 2017). "The result suggested that eIF4E, VEGF-C, MMP-2 promote the lung metastasis of colon cancer." (PMID 27907907, 2016). "Also, we showed that genistein strongly suppressed the metastatic potency of HT29 colon cancer cells via the reduction of MMP2 activity." (PMID 27942504, 2016). "We further demonstrated that MMP2 was high expressed in colon cancer cells." (PMID 27791203, 2016). "In colon cancer, the increased expression and activity of Src tyrosine kinase has been associated with persistent activation of the p130Cas/JNK pathways, the induction of MMP-2 and MMP-9, and invasion/survival in an α1-integrin-dependent fashion." (PMID 26356564, 2015).
colon carcinoma (continued). "Therefore, we suggest that an increased MMP2 expression by pBcl-2-S87 due to PXN-mediated ERK activation plays a crucial role in tumor invasion in colon cancer cells." (PMID 25826088, 2015). "In conclusion, the present study demonstrated for the first time, to the best of our knowledge, that fucoidan inhibited cell growth, migration and sphere formation by suppressing the PI3K/Akt/mTOR pathway and reducing the expression of MMP-2 in human HT-29 colon cancer cells." (PMID 25998232, 2015). "Both MMP9 and MMP2 are required for promotion of liver metastasis of colon cancer in a mouse model To identify the cell type(s) that produce these matrix metalloproteinases, we performed quantitative RT-PCR analyses on the sorted myeloid cells isolated from the liver metastatic foci." (PMID 25326065, 2014). "Furthermore, interfering with TPX2 in colon cancer cell lines decreased cell proliferation and also affected cell migration and invasion as well as expression of the metalloproteinase MMP-2." (PMID 25368990, 2014). "The data suggest that TXP2 may be a potential target in colon cancer therapy due to its ability to modulate downstream MMP2 expression and activity." (PMID 24341487, 2013). "Since miR-29b plays a role in regulating the migration of cancer cells, we hypothesized that HAG induces miR-29b expression to target matrix metalloproteinase-2 (MMP-2) thereby suppressing the migration of colon cancer cells." (PMID 24130681, 2013). "In addition to degrading ECM components, MMP’s were shown to confer apoptosis resistance by modulating Fas-FADD mediated death signaling and cleavage of Fas by MMP-2 resulted in decreased sensitivity of HT-29 colon carcinoma cells to Fas mediated apoptosis." (PMID 22962598, 2012). "Furthermore, the data reported here show that LPE is able to inhibit the rIL-6-dependent cell migration and invasiveness in human primary T88 and T93 colon cancer cells via the up-regulation of MMP-2 expression, and that the observed effects correlate with the STAT3 phosphorylation levels." (PMID 34885656, 2021). "Finally, we counted the expression of MMP2 in 20 pairs tissues of colon cancer patients." (PMID 34976953, 2021). "Thus, our study detected the MMP2 expression in colonic tumors by qPCR." (PMID 33201893, 2020). "Moreover, we show, for the first time, that the activation of Nrf2/HO-1 axis could be also responsible for colon cancer progression through the acquisition of a metastatic behavior, as demonstrated by the increase in the levels of MMP-2 and VEGF." (PMID 30974805, 2019). "Furthermore, MMP-2 was confirmed to promote the lung metastasis of colon cancer cells." (PMID 27907907, 2016). "Moreover, 25-OHC in combination with IL-1β has been shown to stimulate human colon carcinoma cells (Caco-2) to produce IL-8, which in turn is a promoter of angiogenesis by stimulating endothelial cells proliferation, survival, migration, and MMP-2 production." (PMID 21070649, 2010). "It has been previously shown that MMP2 and MMP9 are upregulated by hypoxia in breast and colon cancer cells via a HIF1-dependent mechanism." (PMID 41228316, 2025). "We found that both MMP2 and MMP9 were significantly reduced in both colon cancer cell lines, suggesting that changes at the protein level were more pronounced than at the gene level." (PMID 41226554, 2025). "AAM inhibits VM formation in colon cancer cells through the inhibition of the expression of HIF-1α, thereby reducing the pro-angiogenic effect of MMP2." (PMID 40563539, 2025). "Since miR-29b plays a role in regulating the migration of cancer cells, results revealed that HAG induces miR-29b expression to target MMP-2, thereby suppressing the migration of HCT 116, LOVO, and DLD-1 colon cancer cells." (PMID 39858430, 2024).
colon carcinoma (continued). "Very recent research showed that PLE0 also suppressed the expression and enzymatic activity of MMP-2 and MMP-9, while simultaneously increasing the protein and mRNA levels of TIMP-1 in HT-29 and HCT 116 human colon cancer cells." (PMID 39858430, 2024). "MiR-7 has been reported as a regulator of MMP-2 and MMP-9 expression, acting in the invasion and proliferation of human colon cancer by directing the expression of the focal adhesion kinase." (PMID 36901866, 2023). "Prominent MMPs, such as gelatinase A (MMP-2) and gelatinase B (MMP-9), are essential for the proteolytic cascade-driven breakdown of the ECM during colon cancer spread." (PMID 37037467, 2023). "For example, the exposition of mouse colon cancer ES cells to 1% oxygen for 24 h showed an upregulation of HIF-1α and MMP-2 that decreased with the use of HIF-1α siRNA or in knockout HIF-1α−/− cells cultured in normoxic conditions." (PMID 38069210, 2023). "The inhibitory effects of anthocyanins on MMP-2 and MMP-9 expression were also shown in HCT-116 colon cancer cells." (PMID 35883834, 2022). "The TCM monomer composition (i.e., kaempferol) and target proteins MMP1 (ID : P03956), MMP2 (ID : P08253), and MMP9 (ID : P14780), which had a strong correlation with colon cancer, were screened using HERB database." (PMID 36147444, 2022). "Meanwhile, MMP2 and MMP9 expression in siRPL5-transfected colon cancer cells was lower than that of siNC transfection group." (PMID 36384455, 2022). "PEITC inhibited the invasion and migration of human colon cancer HT29 cells by decreasing SOS-1, PKC, ERK1/2, and Rho A which led to the reduction of MMP-2 and MMP-9." (PMID 35368876, 2022). "Nicotine also stimulates angiogenesis and neovascularization in colon cancer through increases in VEGF, 5-LOX, COX-2, and matrix metalloproteinase-2/9 (MMP-2/9)." (PMID 35406504, 2022). "Various studies showed that SPHK1 promotes MMP2 and MMP9 expression in fibroblast‐like synoviocytes and colon carcinoma RKO cells." (PMID 34262394, 2021). "The degradation of type IV collagen is found in both invasion and metastasis, and the expression of MMP-2 and MMP-9 is significantly higher in colon cancer cells." (PMID 34572476, 2021). "For example, in colon cancer, chloride intracellular channel 1 can regulate cancer cell migration and invasion through ROS–ERK–matrix metalloproteinase 2 (MMP2) pathway." (PMID 33968728, 2021). "The levels of MMPs including MMP-2, MMP-9, MMP-11, and MMP-19 are elevated in the colon cancer patients as compared to normal individuals." (PMID 34096454, 2021). "We explored the links between MMP2 and MMP9 expression and related immunological markers in colon cancer by TIMER." (PMID 34830271, 2021). "Consistent with our results, red ginseng extract has been shown to inhibit MMP2 and MMP9 expression in colon cancer cells and adipocytes." (PMID 35011007, 2021). "Remarkably, upregulation of CPT1A in CAFs promotes the proliferation and invasion of colon cancer by enhancing the ability of CAFs to secrete CCL2, VEGF‐A, and MMP2." (PMID 33528867, 2021). "Our results are consistent with it, and ELISA assays showed that astragalin inhibited cancer cells’ migration by promoting the downregulation of MMP-2 and MMP-9 expression in colon cancer cells." (PMID 33953676, 2021). "A previous study reported that PARPs activate the metastasis-related genes integrin β-1, matrix metallopeptidase-2 (MMP-2), and MMP-9 through the nuclear factor kappa-light-chain pathway in colon cancer." (PMID 34830749, 2021). "A previous report showed that HIF-1α promotes invasion by regulating the expression of MMP-2 and uPAR in HCT116 colon carcinoma cells." (PMID 32867190, 2020). "Studies have revealed that MMP2 and MMP9 promote the degradation of the extracellular matrix, proliferation, and invasion of colon cancer cells." (PMID 32029709, 2020).